NRAS (NRAS proto-oncogene, GTPase)
Description:
Signal transducer in the Ras-MAPK signaling pathway that regulates cell proliferation and survival. Ras proteins bind GDP/GTP and possess intrinsic GTPase activity. Recognized by LZTR1 that mediates its ubiquitination by a BCR (BTB-CUL3-RBX1) E3 ubiquitin-protein ligase complex.
Synonyms: N-ras; ALPS4; CMNS; NCMS; NRAS1; NS6; RALD1
Tractability: Small molecule: a drug acting on it is in phase 2 or 3 trials; a structure with a bound ligand is known; a high-quality ligand is known. Antibody: UniProt places it where antibodies can reach, with high confidence; its Gene Ontology location is reachable by antibodies, with high confidence. PROTAC: UniProt records ubiquitination sites on it; ubiquitination databases record sites on it; its protein half-life has been measured; a small molecule that binds it is known.
Target class: Enzyme; Hydrolase
Gene: Protein-coding gene on chromosome 1 (114,704,469 to 114,716,771, reverse strand). Ensembl gene ENSG00000213281.
Subcellular location: Cell membrane; Golgi apparatus membrane
Subcellular location (Human Protein Atlas): Plasma membrane; Cytosol
Pathways (Reactome):
Signal Transduction: Activated NTRK2 signals through FRS2 and FRS3; Activated NTRK2 signals through RAS; Activated NTRK3 signals through RAS; Downstream signal transduction; EGFR Transactivation by Gastrin; Erythropoietin activates RAS; Estrogen-stimulated signaling through PRKCZ; FRS-mediated FGFR1 signaling; FRS-mediated FGFR2 signaling; FRS-mediated FGFR3 signaling; FRS-mediated FGFR4 signaling; GRB2 events in EGFR signaling; GRB2 events in ERBB2 signaling; Insulin receptor signalling cascade; MAP2K and MAPK activation; MET activates RAS signaling; Negative regulation of MAPK pathway; PTK6 Regulates RHO GTPases, RAS GTPase and MAP kinases; RAF activation; RAF/MAP kinase cascade; RAS processing; Regulation of RAS by GAPs; SHC-mediated cascade:FGFR1; SHC-mediated cascade:FGFR2; SHC-mediated cascade:FGFR3; SHC-mediated cascade:FGFR4; SHC-related events triggered by IGF1R; SHC1 events in EGFR signaling; SHC1 events in ERBB2 signaling; SHC1 events in ERBB4 signaling; SOS-mediated signalling; Signaling by SCF-KIT; Signalling to RAS; VEGFR2 mediated cell proliferation; p38MAPK events
Disease: Constitutive Signaling by EGFRvIII; Constitutive Signaling by Ligand-Responsive EGFR Cancer Variants; Constitutive Signaling by Overexpressed ERBB2; Paradoxical activation of RAF signaling by kinase inactive BRAF; RAS signaling downstream of NF1 loss-of-function variants
and 28 more pathways
Gene Ontology:
Molecular function: GTPase activity; protein binding; protein-containing complex binding; G protein activity; GTP binding
Biological process: positive regulation of endothelial cell proliferation; Ras protein signal transduction; MAPK cascade; positive regulation of cell population proliferation; positive regulation of Ras protein signal transduction; signal transduction
Cellular component: extracellular exosome; Golgi apparatus; Golgi membrane; membrane; plasma membrane; cytosol; endoplasmic reticulum membrane; tertiary granule membrane
Genetic constraint (gnomAD): Loss-of-function variants: 5 observed, 19.11 expected, observed/expected ratio (o/e) 0.26, 90% interval 0.14 to 0.55. The upper end of that interval is the gene's LOEUF score, 0.55, which puts it in group 2 of 6, group 1 being the genes least tolerant of losing a copy. Missense variants: 139 observed, 232.75 expected, observed/expected ratio (o/e) 0.6, 90% interval 0.52 to 0.69. Synonymous variants: 83 observed, 83.89 expected, observed/expected ratio (o/e) 0.99, 90% interval 0.83 to 1.19.
Gene-disease validity (ClinGen):
ClinGen rates the evidence that NRAS causes each of these diseases.
Noonan syndrome (autosomal dominant): Definitive. Noonan Syndrome (NS) is characterized by short stature, typical facial dysmorphism and congenital heart defects.
cardiofaciocutaneous syndrome (autosomal dominant): Limited. Cardiofaciocutaneous (CFC) syndrome is a RASopathy characterized by craniofacial dysmorphology, congenital heart disease, dermatological abnormalities (most commonly hyperkeratotic skin and sparse, curly hair), growth retardation and intellectual disability.
Costello syndrome (autosomal dominant): Limited. Costello syndrome (CS) is a rare multisystemic disorder characterized by failure to thrive, short stature, developmental delay or intellectual disability, joint laxity, soft skin, and distinctive facial features.
Noonan syndrome with multiple lentigines (autosomal dominant): Limited. A rare multisystem genetic disorder characterized by lentigines, hypertrophic cardiomyopathy, short stature, pectus deformity, and dysmorphic facial features.
Cancer hallmarks: invasion and metastasis (promotes); escaping programmed cell death (promotes); cell replicative immortality (promotes); proliferative signalling (promotes)
Homologues: Orthologues: chimpanzee NRAS (100% identical), dog NRAS (100% identical), macaque NRAS (100% identical), pig NRAS (100% identical), rabbit NRAS (100% identical), guinea pig NRAS (99% identical), mouse Nras (99% identical), rat Kras (95% identical), zebrafish nras (91% identical). Paralogues in human: HRAS (85% identical), KRAS (85% identical), RRAS2 (54% identical), RRAS (53% identical), MRAS (50% identical), RAP1B (50% identical), RAP1A (50% identical), RALA (49% identical), ERAS (49% identical), RALB (48% identical), RIT1 (48% identical), RIT2 (46% identical), and 23 more.
Diseases named in the same sentence as NRAS in open-access papers:
NRAS is named in the same sentence as 412 diseases in open-access papers, as found by Europe PMC text mining. Sharing a sentence is not in itself a finding about the gene and the disease. The quoted sentences say what the papers report.
melanoma (1,680 papers, 1996 to 2026). A malignant, usually aggressive tumor composed of atypical, neoplastic melanocytes. "When melanoma cells are grouped according to their genotype (WT vs. BRAF/NRAS-mutated), treatment with sonidegib results in a significant dose-dependent enhancement in the percentage of cells in the S phase only in mutant cells." (PMID 41596411, 2026). "Consistently, in melanoma cell lines carrying BRAF or NRAS mutation, GLI2 expression was stronger than in wild-type cells." (PMID 41596411, 2026). "The most frequent pathogenic molecular alteration in these melanomas were found in NRAS (25%) and BRAF (25%)." (PMID 41595691, 2026). "Canonical MAPK pathway mutations were common: BRAF V600E and NRAS Q61 variants were detected in many nevi and melanomas and were shared between lesions in 8 of 15 patients, providing direct evidence of clonal continuity." (PMID 41516405, 2026). "NRAS-mutated melanoma had a high incidence, which emphasizes the unmet need to develop therapies and trials for NRAS-mutated melanoma." (PMID 41378737, 2026). "We studied the tumour and metastases of a patient with a melanoma carrying an NRAS mutation, who received chemotherapy and immune checkpoint inhibitor treatment." (PMID 41168392, 2025). "For instance, mutations in genes such as BRAF and NRAS are common in both canine and human melanomas, making canine melanoma a valuable model for studying melanoma-specific immunotherapies." (PMID 40386779, 2025). "The raw RNA sequencing data of DNML1, MFN1, and OPA1 from normal and melanoma samples, associated with NRAS-type mutations, were analyzed from a previous study." (PMID 40141318, 2025). "In a Phase 1a/1b clinical trial, monotherapy treatment with brimarafenib resulted in a disease control rate (DCR) of 48% and an overall response rate (ORR) of 18%, with notable responses in patients with NRAS‐mutated melanoma." (PMID 41199020, 2025). "To induce melanoma, we combined Cdh1 loss with the NRAS(Q61K) mutation using the Tyr::NRASQ61K/°; Cdkn2a+/− model." (PMID 40500450, 2025). "In a phase I study involving advanced solid tumors, mirdametinib significantly reduced pERK and Ki67 levels in melanoma patients, including those with NRAS mutations." (PMID 41199020, 2025). "We sorted the cell lines for their NRAS-mutation status and identified that 0% of NRAS-WT melanoma cell lines showed strong dependency on NRAS-mRNA expression." (PMID 40473796, 2025). "By contrast, NRAS mutation was associated with AHM (40.0% versus 10.8% in pigmented melanoma; p = 0.005) and with NM (41.7% versus 3.3% in SSM; p = 0.001)." (PMID 40867317, 2025). "Among the key drivers of melanoma progression are mutations in the Ras family of small GTPases, particularly NRas, and the dysregulation of downstream signaling pathways." (PMID 41373795, 2025). "NRAS mutations, present in approximately 15–25% of melanomas, define a subset of tumors that are generally more aggressive and associated with poorer outcomes compared to NRAS wild-type disease." (PMID 40981345, 2025). "The drug demonstrated partial responses in melanoma patients, suggesting its potential utility in treating NRAS‐mutated cancers." (PMID 41199020, 2025). "When including other mitogen-activated protein kinase (MAPK) pathway mutations, peppering was observed to be more frequent in BRAF- or NRAS-mutated melanomas." (PMID 41010758, 2025). "NRAS mutation analysis was tested in 25 patients with advanced melanoma; seven of them were positive for Q61X mutation." (PMID 40994966, 2025). "Correlation analysis of killing curves after single drug or combination treatment revealed a significant additive effect for the combination therapy in all tested patient derived NRAS mutated melanoma cell lines in vitro." (PMID 41199020, 2025). "While BRAF V600E mutations are classically associated with acquired nevi and melanoma, mutations in NRAS, particularly affecting the NRAS/MAPK pathway, are frequently detected in CMN." (PMID 40265343, 2025).
melanoma (continued). "On the other hand, NRAS mutations are more common for cutaneous melanomas, occurring in 10–15% of melanomas." (PMID 40447784, 2025). "NRAS, the first proto-oncogene discovered in melanoma, encodes a small GTPase and is mutated in approximately 15–25% of melanomas, the most common mutation being Q61, mainly QR, QL and QK." (PMID 39859576, 2025). "Resistance to vemurafenib has been reported in melanoma patients due to secondary NRAS (neuroblastoma RAS viral oncogene homolog) mutations, which lead to paradoxical MAPK pathway activation and tumor proliferation." (PMID 40141318, 2025). "NRAS mutant melanoma is associated with significantly worse progression-free survival (PFS) compared to NRAS wild-type melanoma, with hazard ratios indicating a higher risk of progression." (PMID 40867277, 2025). "The RAS/RAF/MAPK/ERK signaling pathway is predominantly activated in melanomas through NRAS or BRAF mutations." (PMID 40331942, 2025). "Typically, NF1 and NRAS mutations are considered mutually exclusive in melanomas, as both affect the RAS/MAPK pathway." (PMID 40125165, 2025). "Melanomas harboring NRAS mutations represent 15–25% of all melanomas and behave more aggressively than other melanomas." (PMID 40423070, 2025). "(A) NRAS mutations in melanoma lock the NRAS protein in its active state, driving constitutive activation of the MAPK pathway and promoting cell proliferation." (PMID 41199020, 2025). "Unfortunately, therapies targeting BRAF mutations in melanoma or KRAS mutations have shown limited efficacy in patients with NRAS-mutated tumors." (PMID 39940799, 2025). "The second most frequently mutated RAS oncogene is NRAS, found mutated in many cancers but particularly prevalent in melanoma." (PMID 39858030, 2025). "It was also found that the loss of Tet2 acts in a cooperative manner with mutant NRas, driving melanoma genesis and accelerating melanoma progression." (PMID 40427015, 2025). "The study was conducted in a mouse model with BRAF and NRAS mutations, as well as wild-type melanoma xenografts and allografts of highly metastatic melanoma." (PMID 41178942, 2025). "The role of NRAS mutations, especially in codon 61, is crucial in the development and progression of pCNS melanoma, alongside pathological markers like Melan A and HMB-45." (PMID 40417324, 2025). "Mutations of the BRAF gene are the most frequent, detected in approximately 38.5% of melanomas, while NRAS mutations occur in about 16.4% and KIT mutations in around 10% of cases." (PMID 41007741, 2025). "The expression of DNML1 (encoding the human DRP1 gene, a key regulator of mitochondrial fission) is increased in NRAS-mutated melanoma samples compared to the normal tissues." (PMID 40141318, 2025). "We selected a panel of melanoma cell lines, harboring either mutated or wild type NRAS/BRAF genes, to investigate SPARC promoter activity." (PMID 40943659, 2025). "BRAF and NRAS gene mutations occur at an early point in melanoma pathogenesis and are consistently sustained during further tumor progression, taking part in the pathogenesis of invasive melanoma but also in cooperation with other mutations." (PMID 41049012, 2025). "Previous studies on BRAF‐ and NRAS‐mutated melanomas have identified the co‐occurrence of mutations affecting members of this critical pathway." (PMID 41017066, 2025). "The NRAS (p.G13D) mutation identified in this case is a known activating mutation that can drive melanoma progression through the RAS/MAPK pathway." (PMID 40125165, 2025).
melanoma (continued). "Mutation frequencies also vary across specific anatomical sites, with head and neck melanomas more often showing mutations in NRAS and TERT promoters, and genitourinary or anorectal melanomas showing KITKIT mutations." (PMID 41295253, 2025). "NRAS mutations are common in melanomas and hematological malignancies, whereas HRAS mutations are frequently observed in head and neck squamous cancers (4.7%), as well as urothelial carcinomas (5.9%)." (PMID 41516092, 2025). "Found in nearly 30 percent of cases with melanoma, NRAS oncogenic mutations are the second most common mutation found in melanoma." (PMID 39940799, 2025). "The most striking results of our study were that BRAF and NRAS mutated melanomas were significantly associated with conventional poor prognostic variables than WT melanomas, such as ulceration, higher mitotic rate, NM histotype, and AHM subtype." (PMID 40867317, 2025). "The clinical relevance of the combination of PDPK1 and MEK inhibitors was also demonstrated in the NRAS-mutated xenograft model, indicating the efficiency of the combinatorial strategy for the treatment of melanoma patients with NRAS mutation." (PMID 41369373, 2025). "Previous efforts to target NRAS-mRNA in NRAS-mutant melanoma focused on the mutational site of the NRAS-mRNA sequence." (PMID 40473796, 2025). "(2012) identified BRAF mutations in 50% of melanomas, NRAS mutations in 30%, NF1 mutations in 12–23%, and PTEN mutations in 5–40%, highlighting their role in melanoma progression and therapeutic responsiveness." (PMID 41142596, 2025). "According to a previous study, reactivation of the MAPK pathway caused by BRAF and NRAS alternative splicing conferred BRAFi resistance in melanoma cells." (PMID 40681872, 2025). "Melanomas with NRAS Q61k mutation are less common and more aggressive, with a higher risk of recurrence and metastasis." (PMID 40134855, 2025). "As Spitz melanoma is classified as a non-CSD melanoma and most frequent and exclusive mutations are represented by BRAF and NRAS mutations in melanoma, the molecular profiling becomes even more important in terms of diagnosis and prognosis." (PMID 40870546, 2025). "An important piece of information from our study is the synergistic effect of combining mTOR/PI3K inhibitors with MEK1/2 blockades, especially in NRAS-mutated melanoma, where reciprocal activation limits the efficacy of monotherapy." (PMID 40869090, 2025). "It is also important to recognize that concomitant BRAF and NRAS mutations are exceedingly rare in both melanoma and patients with CLL; therefore, it must be confirmed." (PMID 39940799, 2025). "Other mutations commonly found in melanoma include NRAS (28% of cases), NF1 (14%), and KIT (15-20% in acral and mucosal melanomas)." (PMID 40861441, 2025). "While targeted kinase inhibitors have improved outcomes for patients with BRAF‐mutated melanomas, their efficacy is often short‐lived, and effective treatments for other mutations, such as NRAS, remain scarce." (PMID 41199020, 2025). "Mutations in NRAS or BRAF genes were observed in 80% of melanoma or melanocytic nevus cases, confirming the critical role of the MAPK pathway." (PMID 40932870, 2025). "They analyzed ctDNA levels of BRAF and NRAS mutations in plasma samples from 29 advanced melanoma patients who exhibited disease progression after 12 weeks of anti-PD-1 therapy." (PMID 39859576, 2025). "Collectively, these data provide a strong biologic and clinical rationale for developing panRAF + MEK combinations to mitigate the limitations of monotherapy and result in more complete MAPK pathway inhibition in NRAS mutated melanoma tumors." (PMID 41199020, 2025). "Mutations in BRAF V600E or NRAS, common drivers in melanoma, can paradoxically induce senescence in melanocytes during early transformation stages." (PMID 40926366, 2025).